REST (RE1 silencing transcription factor)
Diseases named in the same sentence as REST in open-access papers (continued):
Sharing a sentence is not in itself a finding about the gene and the disease.
tumor (continued). "Taken together, these data indicate that inhibition of REST decreased the number of functional tumor vessels and increased vascular permeability, thus increasing tumor hypoxia and apoptosis." (PMID 32486064, 2020). "Together with our previous report, the data presented here implicate REST in the regulation of the ES tumor vasculature." (PMID 32486064, 2020). "Quantitative analysis confirmed that down-regulation of REST increased tumor vessel permeability, as FITC-labeled dextran was significantly increased in R1106 and R1606 tumors compared with RC-control tumors (p < 0.01)." (PMID 32486064, 2020). "Taken together with our previous work, our new results confirm that REST is a critical regulator of ES tumor vasculature integrity and function, pointing to REST as a new therapeutic target for ES." (PMID 32486064, 2020). "Immunofluorescence staining of the tumor samples for REST expression confirmed that REST was significantly reduced in the R1106 and R1606 tumors compared with the RC-control tumors." (PMID 32486064, 2020). "These in vivo findings of decreased pericyte coverage of the tumor vessels in the REST-KO tumors are supported by our previous in vitro studies showing that REST regulated the expression of the pericyte markers desmin and NG2 in ES cells." (PMID 32486064, 2020). "We used CRISPR/Cas9 to knock out REST, creating two REST-KO clones with ≥80% reduction in REST expression, confirmed in vitro and in tumor samples." (PMID 32486064, 2020). "In vivo experiments (a subcutaneous BALB/c nude mouse model and a superior mesenteric vein injection BALB/c nude mouse model) suggested that knockdown of REST suppressed growth and metastasis of xenograft tumor." (PMID 31041193, 2019). "Results of subcutaneous tumor model showed that knockdown of REST suppressed xenograft tumor growth in vivo." (PMID 31041193, 2019). "Results of metastatic tumor model showed that knockdown of REST suppressed the liver metastasis and intestine metastasis." (PMID 31041193, 2019). "Gene expression analysis of 81 human SCLC primary tumours with RNA-seq data showed that abnormal high expression of SRRM4 corresponds to lower REST expression." (PMID 31110284, 2019). "A significant difference in CD31 staining and tumor vasculature was observed between REST shRNA1 and control shRNA expressing intracranial (IC) and extracranial (EC) tumors." (PMID 29435175, 2018). "REST mRNA levels were significantly elevated in DIPG tumor samples (n=35) compared to normal brain (n=10)." (PMID 29435175, 2018). "There are other reported targets for miR-106b, such as PTEN, SMAD7 and REST and downregulation of these targets by miR-106b also contributes to tumor progression." (PMID 28422740, 2017). "Like Wnt signaling, REST appears to possess different activities in various tumor or cellular contexts." (PMID 24724054, 2014). "In neural stem/progenitor cells, REST can cooperate with other molecular alterations including MYC over-expression to induce tumor formation in the cerebellum by blocking neuronal differentiation and maintaining the “stemness” of these cells." (PMID 24724054, 2014). "In a subset of tumor samples, we observed a concerted over-expression of REST target genes, and designated this group as REST–less." (PMID 20548947, 2010). "Using 3 control tissue samples and 16 tumors spread among 3 tumor stages, they suggest that REST protein and mRNA levels undergo a stepwise, statistically significant decrease with each increasing tumor stage." (PMID 20548947, 2010). "To determine whether loss of REST function occurs exclusively in neoplastic mammary tissue, we used the 24-gene signature to screen 66 non-neoplastic mammary samples, half of which came from non-tumor bearing normal breast and half of which were adjacent normal stroma from a tumor-bearing breast." (PMID 20548947, 2010).
tumor (continued). "This method compares the expression of a set of experimentally-defined REST target genes (termed “S”) between REST–less and RESTfl tumors, and assesses the relative enrichment of ‘S’ in either tumor group." (PMID 20548947, 2010). "After further analysis of over 700 additional tumors of varying grade, stage, and eventual recurrence, we find that REST mRNA levels are invariant with any of these conventional measures of tumor aggression." (PMID 20548947, 2010). "The perhaps most unexpected finding was the identification of REST as a tumor suppressor in an unbiased screen for suppressors of epithelial cell transformation and thus tumorigenesis." (PMID 18959489, 2008). "Recent studies revealed that REST/NRSF exhibits ubiquitous presence and plays roles in neurogenesis, neural plasticity, tumor suppression, and cancer progression through transcription regulation." (PMID 17555596, 2007). "Indeed, expression of the transcription repressor REST negatively correlates with tumor cell content and is thus depleted in tumors." (PMID 40410286, 2025). "Given the critical role that PRICKLE1 plays in the stability of REST, the long-term repression of this tumor suppressor pathway by environmental estrogens could trigger genetic and epigenetic instability that promotes uterine fibroid pathogenesis." (PMID 39314474, 2024). "Additionally, the expression of NE marker SYP was reduced in xenograft tumor tissues exhibiting REST overexpression." (PMID 38777812, 2024). "In epithelial cancer cells, REST has been reported to act as a tumor suppressor." (PMID 38777812, 2024). "Previous studies have reported REST as both a tumor promoter and tumor suppressor, indicating that REST regulation might have significant physiological and pathological consequences." (PMID 39039049, 2024). "These investigations suggest that REST may serve as a central regulator in tumor occurrence and development, making it a potential diagnostic and therapeutic target in various types of cancer." (PMID 37892159, 2023). "It is important to consider that in non-neuronal tumours, although loss of function of REST has been frequently reported in cancer, this not always lead to the de-repression of its target genes, suggesting an even more complex mechanism." (PMID 37301955, 2023). "The altered REST splicing was found to mediate the anti-tumor effects of SRRM4 targeting in SCLC." (PMID 37892159, 2023). "Moreover, downregulation of REST inhibits the self-renewal potential and tumor-initiating capacity of GBM cells." (PMID 34859007, 2021). "In this study, we observed that the low REST expression gradually decreased with the increase of degree of malignant tumor, which indicated that REST may be an important regulatory gene for tumor occurrence and development." (PMID 33834072, 2021). "Therefore, we selected miR-129 and miR-137, which can effectively regulate REST expression and have tumor inhibitory effects, for our further research." (PMID 34859007, 2021). "Our data suggest that REST elevation in tumor cells may promote VM by driving VEGFR1 expression and possibly activating the protein kinase C alpha pathway." (PMID 33469989, 2021). "Most importantly, our findings suggest that REST‐driven modulation of tumor vasculature may contribute to the increased incidence of metastasis and poor survival in patients with SHH‐α and SHH‐β MBs." (PMID 33469989, 2021). "Inhibiting REST also altered the morphology of the tumor vessels." (PMID 32486064, 2020). "We therefore quantified tumor hypoxia and apoptosis in the REST-KO and RC-control tumors." (PMID 32486064, 2020). "Inhibiting vascular function by blocking REST may also compromise the tumor’s ability to recover and regrow following chemotherapy or radiation therapy, as the oxygen and nutrients required for recovery may not be delivered." (PMID 32486064, 2020).
tumor (continued). "In addition to analyzing the effect of REST knockout (KO) on tumor growth and vascular morphology, we evaluated the effect of REST KO on lung metastasis, vascular perfusion, and vascular permeability." (PMID 32486064, 2020). "In tumor growth, REST has a dual function depending on the cellular context." (PMID 32486064, 2020). "Additionally, the TSPY2/REST complex induces transcriptional repression of TrkC and restores the tumor inhibitory activity of TGF-β." (PMID 31936239, 2020). "Additionally, the depletion of REST expression was performed in vitro, which lacks important factors of the tumor microenvironment." (PMID 32720471, 2020). "In addition, Plk1 can also modulate oncogenic signaling pathways such as the PI3K-MEKK, or dampening the function of well-known tumor suppressors such as PTEN or REST." (PMID 30862113, 2019). "REST acts as a major tumor suppressor through its gene-silencing action." (PMID 31110284, 2019). "We also observed both the ETS (z-score = 9.9) and REST (z-score = 20.52) families of TFs, which reaffirmed our hypothesis that these lncRNAs are involved in tumour progression and neuronal pathways." (PMID 29757368, 2018). "We recently discovered that USP15 controls stability of the RE1-silencing transcription factor (REST), a context-dependent tumour suppressor or oncogene, which is acutely degraded at mitosis before being rapidly replenished in early G1 in a USP15-dependent manner." (PMID 29429988, 2018). "REST can also act as a tumor suppressor in carcinomas including lung, breast and colon." (PMID 26341630, 2015). "Its regulation by βTRCP is consistent with the known role of βTRCP in responding to DNA damage, and may help explain the oncogenic effect of βTRCP overexpression (along with other known tumor suppressor substrates of βTRCP, such as REST)." (PMID 26091241, 2015). "The present study showed that miR-29a, also a tumor suppressor, may be a safer choice to arrest REST expression and balance the tumor formation in cell therap." (PMID 24841827, 2014). "Remarkably, a RNAi-based genetic screen identified a role for NRSF/REST as a tumor suppressor." (PMID 23907384, 2013). "Examination of REST mRNA identified a truncated splice variant of REST present in the REST–less tumor population, but not other tumors." (PMID 20548947, 2010). "Importantly, a recent study has identified REST as a tumour suppressor and has shown that a defective REST gene can be tumourigenic." (PMID 16265346, 2005). "To characterize the result of a yet unknown tumor initiating event, we performed RNA sequencing and revealed a novel transcriptomic signature of siNETs defined by low expression of the transcription repressor REST." (PMID 40410286, 2025). "Apart from its regulated genes, REST itself could promote tumor suppression by methylation." (PMID 40006989, 2025). "However, REST has also been shown to be a tumor suppressor in mammary epithelial cells." (PMID 35177031, 2022). "Among WNT, Group 3, and Group 4 MB tumor samples, a positive correlation between REST and VEGFR1 was detected when all Group 4 tumors were collectively considered (r = 0.16, P = 0.005), but a statistically significant correlation could not be detected in the individual subtypes of Group 4 tumors." (PMID 33469989, 2021). "Therefore, REST inhibition may compromise the ability of ES to contribute to the needed pool of vascular pericytes for tumor vascular expansion in an effort to recover from damage and cell death caused by chemotherapy or radiation therapy." (PMID 32486064, 2020). "Interestingly, H&E sections also seemed to suggest REST-dependent increases in tumor vasculature." (PMID 29435175, 2018). "In effect, we may have underestimated the number of tumor samples with REST protein elevation." (PMID 29435175, 2018). "Thus our molecular biology findings have the potential to be of clinical importance in cancer, and expands the current knowledge about the mechanisms whereby REST might exert its tumour suppressor role." (PMID 26647819, 2015).
tumor (continued). "However, it is dangerous in tumor formation, because REST is regarded as a tumor suppressor." (PMID 24841827, 2014). "Repression of Wnt signaling by REST may also contribute to tumor suppression." (PMID 18959480, 2008). "Knockdown of REST in GBM stem cells impaired their self-renewal capacity, reduced tumor invasiveness, and increased survival in transplanted mice." (PMID 40479062, 2025). "Further Western blotting and IHC of tumor tissues further confirmed suppression of OPRK1, SLC9A3R1, NE, autophagy, and EMT markers, together with restoration of REST protein levels." (PMID 41353213, 2025). "In our study, the ferroptosis pathway in GSCs, mediated by REST, LRSAM1, and SLC40A1, was morphologically identified through immunohistochemical staining of orthotopic xenograft tumor specimens." (PMID 39039049, 2024). "The upregulation of lncRNA ITIH4-AS1 in colorectal cancer enhances RE1 silencing transcription factor (REST) downregulation or depletion, which consequently upregulates ITIH4-AS1 and promotes tumor proliferation and metastasis through JAK/STAT3 pathway." (PMID 39136000, 2024). "For this reason, we analyzed the expression of REST and HAR1A in primary GBM cells derived from the tumour core and from the invasive margin of the same patient (patient 28)." (PMID 39602392, 2024). "Among these 10 genes HDAC1, CASP3, REST, HMG20B, FZD7,GNAI3, FZD1 and EPHB4 had elevated expression in tumor group compared to the normal group, while KCNJ9 and SCRT1 were decreased." (PMID 38629068, 2024). "REST, HAR1A, and HAR1B were all differentially expressed between the tumour core and periphery samples." (PMID 39602392, 2024). "Vivo fluorescence imaging showed a significant reduction in tumor volume and size in mice treated with erianin in combination with TMZ, while GSCm01R cells overexpressing REST or SLC40A1 exhibited increased tumor volume and size." (PMID 39039049, 2024). "Conversely, relative to normal solid tissue samples, REST was upregulated in primary and recurrent tumour samples and HAR1A / HAR1B were downregulated in both primary and recurrent tumours." (PMID 39602392, 2024). "Phenotypically, REST overexpression increases ADT sensitivity, represses NE genes, inhibits colony formation in culture, and xenograft tumor growth of PCa cells." (PMID 37886478, 2023). "High REST expression was positively correlated with higher WHO grade, IDH status (WT), 1p/19q codeletion (non), histological type (GBM), tumor status (with tumor), and primary therapy outcome (SD-PD) (all p < 0.001)." (PMID 34859007, 2021). "By analyzing the TCGA-KIRC dataset, we observed that REST was low expressed in KIRC, and its expression gradually decreased with patients' higher historical level and tumor level." (PMID 33834072, 2021). "Targeting REST and ETS1 for the therapeutic modulation of tumor angiogenesis is a topic for future studies." (PMID 33469989, 2021). "We previously showed that inhibiting REST expression in TC71 and A4573 ES cells using shRNA slowed tumor growth and altered vascular morphology." (PMID 32486064, 2020). "To confirm and extend these investigations focusing on the role of REST in tumor vascular expansion and function, we used CRISPR/Cas9 technology to knock out REST expression in ES cells." (PMID 32486064, 2020). "Results of in vitro and in vivo experiments indicated that REST knockdown suppressed metastatic ability of the PANC-1, AsPC-1 cell lines, and nude mice tumor model." (PMID 31041193, 2019). "Through RNA splicing, SRRM4 simultaneously reprograms REST functions to confer a neuroendocrine phenotype in AdPC cells and re-directs MEAF6 functions to stimulate tumor cell proliferation and invasion." (PMID 28427194, 2017). "Notably, in H1 ESCs the REST binding patterns at all of these genes (except LAMA2) matched with those in the tumor cell lines, suggesting that REST regulation of these genes may have a role in cell proliferation, since active growth is a common feature of ESCs and tumor cells." (PMID 24922058, 2014).
tumor (continued). "Significantly, REST is highly expressed in self-renewing tumorigenic-competent GBM cells and its knock down strongly reduces their self-renewal in vitro and tumor-initiating capacity in vivo and affects levels of miR-124 and its downstream targets." (PMID 22701651, 2012). "Here, we report that REST is expressed in human GBM specimens and that its downregulation strongly impairs self-renewal and tumor-initiating capacity of GBM cells." (PMID 22701651, 2012). "We found REST to be expressed in GBM specimens, its presence being particularly enriched in tumor cells in the perivascular compartment." (PMID 22701651, 2012). "We delineated the intra-tumor heterogeneity (ITH) and the relationship between tumor and stroma, which identified a RE1 silencing factor (REST)-mediated regulatory axis in a subset of patients that may have superior benefit from ICI therapy." (PMID 39231924, 2024). "It was shown that the upregulation of lncRNA ITIH4-AS1 leads to downregulation or depletion of RE1 silencing transcription factor (REST) in CRC, which consequently promotes ITIH4-AS1 expression and induces tumor proliferation and metastasis through JAK/STAT3 pathway." (PMID 39136000, 2024). "In this latter context, REST has the role of an oncogene in neural tissues, and a tumor suppressor in non-neural tissues." (PMID 38542313, 2024). "When examining tumor characteristics and REST expression, there was a statistically significant negative correlation between REST expression in the glandular nuclei and ER percentage in the tumor (Spearman r: −0.44, p = 0.01)." (PMID 39273639, 2024). "One may hypothesize that specific REST target(s) that become derepressed are actually “gearing up” the GBM cells for fatty acid uptake, storage or use to meet tumor’s increased energy demands." (PMID 38609948, 2024). "Given the different role of REST in neuronal and non-neuronal tissues, we focused on alterations with opposite DNA methylation pattern between PA Discovery and the other analysed tumours." (PMID 37301955, 2023). "Since REST plays a crucial role in the regulation of neuronal-related genes, we decided to analyse the DNA methylation pattern at NRSE in the previously analysed tumours." (PMID 37301955, 2023). "Studies have shown that G protein signaling 16 (RGS16) can act as a tumor suppressor by inhibiting the growth of PI3K dependent breast epithelial cells, while inhibiting PI3K/AKT downregulates REST expression and induces NE markers in LNCaP, PC3 and LNCaP95 cells." (PMID 36686485, 2022). "In our studies, the major role of SCYL1 seems promoting BC tumor cell proliferation and migration, whether SCYL1 promotes BC through degradation of the REST warrants further investigations." (PMID 36290821, 2022). "In vitro angiogenesis assays showed that a reduction in ETS1 expression in DAOY‐R caused a significant decline in tube formation, as well as a decrease in tumor endothelial cell colocalization at the tubes, confirming the involvement of ETS1 in this process under conditions of REST elevation." (PMID 33469989, 2021). "Finally, comparisons of tumor samples with normal cerebella made using GSE data sets revealed upregulation of CD31 in MB samples and a positive correlation with REST expression in SHH‐MBs." (PMID 33469989, 2021). "While knockout of REST did not alter tumor cell proliferation in vitro, REST knockout reduced tumor growth and metastasis to the lung in vivo and altered tumor vascular morphology and function." (PMID 32486064, 2020). "Since the growth of ES tumors in vivo was not explained by an effect on tumor cell proliferation, we next evaluated the tumor vasculature morphology in the R1106 and R1606 REST-KO and RC-control tumors, first by staining with CD31." (PMID 32486064, 2020). "We also showed that inhibition of REST expression by shRNA reduced tumor growth and increased tumor hypoxia and apoptosis without modifying the expression of EWS-FLI-1 or decreasing cell proliferation in vitro." (PMID 32486064, 2020).